ADAM33 (ADAM metallopeptidase domain 33)
Diseases named in the same sentence as ADAM33 in open-access papers (continued):
Sharing a sentence is not in itself a finding about the gene and the disease.
asthma (continued). "Recently, it has been reported that a peptide derived from APP is cleaved by α disintegrin and metalloproteinase 33 (ADAM33), which is an asthma susceptibility gene." (PMID 20513247, 2010). "There has been a report that APP is cleaved by α disintegrin and metalloproteinase 33 (ADAM33), which is an asthma susceptibility gene." (PMID 20513247, 2010). "ADAM33 polymorphisms have been associated with asthma risk in various populations, including Korea, Thai, Han Chinese and Japanese, who are closely related with Korean population, especially Han Chinese and Japanese." (PMID 20513247, 2010). "Further research on ADAM33 should clearly involve functional studies to elucidate the roles of ADAM33 SNPs in lung function loss, asthma, and COPD." (PMID 20003279, 2009). "Since the first report of an association between ADAM33 polymorphisms and asthma in two Caucasian populations from the UK and the USA, a number of replication studies have been published with differing results." (PMID 20003279, 2009). "In 2002, van Eerdewegh and coworkers identified ADAM33 as a susceptibility gene for asthma and bronchial hyperresponsivess on chromosome 20 p using positional cloning techniques." (PMID 19284602, 2009). "ADAM33 (a disintegrin and metalloproteinase 33) has been one of the most exciting candidate genes for asthma since its first association with the disease in Caucasian populations." (PMID 20003279, 2009). "In previous studies, it has been shown that polymorphisms in the ADAM33 gene play a role not only in asthma susceptibility, but in its progression." (PMID 20003279, 2009). "Additional studies demonstrated that SNPs within the ADAM33 locus are associated with accelerated decline of lung function in the general population and in asthma patients." (PMID 20003279, 2009). "Since that original publication several studies have replicated the association of ADAM33 with asthma." (PMID 19284602, 2009). "ADAM-33 was one of the first ADAM proteinases to be identified as an asthma susceptibility gene after an ambitious study based on a vast genome screening." (PMID 20034386, 2009). "In a cohort of 200 asthma patients followed over 20 years, Jongepier and coworkers genotyped 8 SNPs in ADAM33 and found that the rare alleles of the SNPs S2, T1 and T2 of ADAM33 were associated with an excess decline in FEV1." (PMID 19284602, 2009). "ADAM33, on chromosome 20p13, was identified by positional cloning and was shown to be associated with asthma and bronchial hyper-responsiveness." (PMID 19284602, 2009). "In parallel, genetic variants in ADAM33 were found associated with asthma and psoriasis, two diseases characterized by tissue remodelling." (PMID 18560587, 2008). "Recently, several SNPs in the ADAM33 gene have been shown to be significantly associated with asthma, BHR, and atopy." (PMID 18778489, 2008). "Polymorphisms in ADAM33, the first gene identified in asthma by positional cloning, have been recently associated with psoriasis." (PMID 18560587, 2008). "Data available in the French EGEA study (Epidemiological study on Genetics and Environment of Asthma, bronchial hyperresponsivensess and Atopy) give the opportunity to attempt to replicate the association between ADAM33 and psoriasis in 2002 individuals." (PMID 18560587, 2008). "Most patients with asthma also have rhinitis, which suggests the concept of 'one airway, one disease.' A disintegrin and metalloproteinase 33 (ADAM33) is the first asthma-susceptible gene to be discovered by positional cloning." (PMID 18778489, 2008). "A number of studies have been conducted to replicate the original findings, some confirming and others refuting the association of ADAM33 with asthma." (PMID 18778489, 2008). "To date, most data available for ADAM33 and asthma have been obtained from Caucasians, but few data on ADAM33 SNPs associated with asthma and atopic disease are available for Asian populations." (PMID 18778489, 2008).
asthma (continued). "The study by van Eerdewegh was the first to show that ADAM33 polymorphisms (Q-1, S1, ST+4, ST+7, V-1, and V4) and haplotypes were associated with asthma in Caucasian families." (PMID 18778489, 2008). "Nevertheless, our findings can be the source of valuable physiological insights, since several ADAM33 SNPs have been found to be associated with asthma and with bronchial hyper-responsiveness in Caucasians, in African Americans and in Hispanics." (PMID 17878941, 2007). "The data presented demonstrate that a disease-associated SNP within ADAM33, an asthma susceptibility gene, does have functional consequences." (PMID 17640346, 2007). "The same situation is observed in the case of asthma and psoriasis, where the association with ADAM33 is stronger when combinations of SNPs are examined." (PMID 17878941, 2007). "Using these approaches, the first asthma susceptibility gene, ADAM33 (A Disintegrin And Metalloprotease 33), was discovered in an outbred population." (PMID 17640346, 2007). "This study demonstrates for the first time that an ADAM33 asthma-associated SNP, BC+1, does have functional consequences." (PMID 17640346, 2007). "Currently, 42 disease-associated SNPs have been identified within the asthma-associated ADAM33 gene." (PMID 17640346, 2007). "Multiple SNPs and SNP pairs that were typed in ADAM33 were found to be associated with asthma and bronchial hyperresponsiveness." (PMID 17640346, 2007). "While these genetic studies have identified ADAM33 alleles that are associated with an asthma phenotype, the mechanistic role of the SNPs in the development of the disease symptoms has yet to be determined." (PMID 17640346, 2007). "ADAM33 polymorphisms have also been shown to play a role in the development of asthma and also in disease progression via effects on airway remodelling." (PMID 16948840, 2006). "As a potential atopy/asthma susceptibility locus, ADAM33 was considered as a candidate gene for T1D because atopic illness and T1D have been inversely associated." (PMID 16519819, 2006). "As a proof-of-principle, we tested the system with one gene recently linked to asthma: ADAM33 in the cytogenetic band 20p13." (PMID 16115313, 2005). "The rs2280091 variant of the ADAM33 gene, although its significance varies across populations, has been consistently linked to an increased risk of allergic and functional asthma, with the G allele correlating with greater susceptibility and pulmonary function decline." (PMID 41373738, 2025). "The distinct inflammatory microenvironments, immune pathways, and mechanisms of airway injury in asthma and CF therefore offer a plausible biological explanation for how the same ADAM33 variant could manifest opposite clinical effects." (PMID 41373738, 2025). "Variants of the ADAM33 gene have been widely associated with bronchial hyperresponsiveness, persistent inflammation, and a progressive decline in lung function in respiratory diseases such as asthma." (PMID 41373738, 2025). "Initially identified as an asthma susceptibility gene, ADAM33 is expressed in vascular smooth muscle cells and tissues including the lungs, where it contributes to airway remodeling, angiogenesis, and chronic inflammation, for instance, in cases of allergic rhinitis." (PMID 41373738, 2025). "Moreover, another anchor point is the relationship between IgE concentration with asthma profile as well as with ADAM33 polymorphism." (PMID 38396994, 2024). "Hence, the aim of this study was to identify the association between ADAM33 polymorphisms and asthma, disease severity, and treatment responsiveness to ICS+LABA." (PMID 36766510, 2023). "We went on to examine whether the ADAM33 SNPs were associated with a healthy outcome, in terms of improved lung function and treatment responsiveness, in the asthma patients treated for three months with ICS+LABA." (PMID 36766510, 2023). "Of the studied ADAM33 SNPs, rs2853209 showed an association with asthma." (PMID 36766510, 2023).
asthma (continued). "We observed that the ADAM33 SNP rs2853209 minor allele (T) was protective against asthma." (PMID 36766510, 2023). "Another possibility could be the influence of polymorphisms of the ADAM33 gene that may lead to the varied expression of ADAM33, which may affect smooth muscle function and impact the response to asthma treatment." (PMID 36766510, 2023). "Upregulation of ADAM33 was implicated in airway vascular remodeling in asthma." (PMID 38071234, 2023). "Taken together, ADAM33 is considered an important element in the promotion of asthmatic response, and therefore, genetic variations throughout its gene may be linked to asthma susceptibility and severity." (PMID 36292755, 2022). "ADAM33 has been identified as an asthma susceptibility gene." (PMID 35955554, 2022). "ADAM33 is the earliest positionally cloned asthma susceptibility gene, which means that its exact arrangement in the genome was established before the gene’s purpose could be established." (PMID 36225476, 2022). "Genetic polymorphisms in genes including alarmin cytokines (TSLP and IL-33) type 2 cytokines (IL-4, IL-13) and other inflammatory-related proteins (HLA, ADAM33), and vitamin D receptor have been shown to enhance, or reduce, the risk and severity of asthma in individuals." (PMID 36292755, 2022). "The aim of this study was to determine whether there is an association between IgE levels and the genetic polymorphisms of the ADAM33 gene (T1, T2, T + 1, V4, S1, S2, and Q-1) in asthma patients of Jordanians." (PMID 33922216, 2021). "The ADAM33 gene was found to be associated with asthma and airway hyperresponsiveness." (PMID 34880399, 2021). "Disintegrin and metalloproteinase 33 (ADAM33), the first asthma-susceptible gene identified by positional cloning, was the only gene identified with significant methylation level differences between the groups at the CpG site level, amplicon level and gene level." (PMID 33933154, 2021). "Among the genes, IL17A and ADAM33 have been implicated in the severity of asthma." (PMID 33784348, 2021). "Notably, ADAM33 has been extensively reported as a susceptibility gene in bronchial hyperresponsiveness, asthma and AR." (PMID 33933154, 2021). "However, we are not aware of any reports of a functional correlation between any ADAM33 SNP alleles and ADAM33 protein levels in bronchial smooth muscle cells, bronchial lavage fluids, or serum in patients with asthma." (PMID 30186568, 2018). "ADAM33 is known to be involved in branching morphogenesis in the fetal lung, and polymorphic variations in this gene are associated with the pathophysiology of chronic obstructive pulmonary disease, airway remodeling, and hyperresponsiveness in asthma." (PMID 30186568, 2018). "The contribution of ADAM33 gene polymorphisms to the risk of asthma is controversial." (PMID 30186568, 2018). "ADAM33 is the first asthma susceptibility gene to be identified by positional cloning." (PMID 28918018, 2017). "The relevant studies about the relationship between ADAM33 gene polymorphisms and childhood asthma were searched from electronic databases and the deadline of retrieval was May 2016." (PMID 28876365, 2017). "Therefore, more keywords should be used to retrieve more studies for further evaluate the relationship between ADAM33 polymorphism and childhood asthma." (PMID 28876365, 2017). "This study may provide new perspectives in explaining the significance of ADAM33 for predicting the risk of childhood asthma." (PMID 28876365, 2017). "Because the asthma susceptibility gene a disintegrin and metalloprotease 33 (ADAM33) has been linked to BHR158 and has been shown to cause bronchial smooth muscle contraction, there is the potential for multifactorial indirect genetic effects on epithelial barrier function." (PMID 28583446, 2017). "Recently, several ADAM33 polymorphisms have been shown to be associated with childhood asthma." (PMID 28876365, 2017).
asthma (continued). "Therefore, inhibition of ADAM33 represents an attractive disease-modifying therapeutic strategy for treating the root cause of asthma in many patients." (PMID 28918018, 2017). "ADAM33 on chromosome 20p13, was the first asthma susceptibility gene discovered." (PMID 27658857, 2016). "If the interaction is genuine, it could provide new insight into the biological role of ADAM33 or its neighboring genes in asthma susceptibility, and may also emphasize GLI2 as a new gene of investigation for asthma." (PMID 27387956, 2016). "In this report, we have defined the function of ADAM33 as a local tissue susceptibility gene for asthma and have uncovered a substantial interaction between sADAM33-mediated airway remodeling and sensitivity to allergen exposure, leading to allergic inflammation and BHR in early life." (PMID 27489884, 2016). "Interestingly, rs910652 is located approximately 78 kilobases upstream of ADAM33, which is one of the most well-studied susceptibility loci for asthma." (PMID 27387956, 2016). "As a susceptibility gene close to the origin of asthma, ADAM33 is a potential therapeutic target." (PMID 27489884, 2016). "Such a paradigm might explain the association of ADAM33 polymorphism with progression of preschool wheeze into childhood asthma." (PMID 27489884, 2016). "The replication of the negative association of the CG/GG-genotype of rs528557 ADAM33 with childhood asthma in an independent birth cohort study confirms that a compromised ADAM33 gene may be implicated in the progression of wheeze into childhood asthma." (PMID 25768087, 2015). "We conducted a study in an Indian population and assessed association for 14 ADAM33 SNPs (F+1, V4, ST+4, S2, ST+5, V2, T2, T1, BC+1, Q-1, S1, S+1, V-3, and T+1) and found 8 SNPs (F+1, V4, ST+4, S2, ST+5, T2, T1, and S1) in association with asthma." (PMID 24817794, 2014). "While studies, including association studies and meta-analyses, have suggested that several ADAM33 gene polymorphisms (e.g., ST+5, S2, and T1) are important in conferring susceptibility to asthma, the data are controversial, and the true causative variants have not been identified yet." (PMID 24817794, 2014). "However, a genome-wide association studies (GWAS) of Spanish individuals revealed that among 19 selected tag SNPs of ADAM33, only one SNP (rs2787095) was associated with asthma." (PMID 24751681, 2014). "In the present study thirteen SNPs of ADAM33 were analyzed in an Eastern Chinese population, particularly in asthma patients with the distinct palm pattern, to clarify the ADAM33 association with asthma and the genetic basis of the association between asthma and palm dermatoglyphs." (PMID 24141861, 2013). "It was suggested that in asthma patients the distinctive palm pattern was considered to be a biomarker for ADAM33 polymorphisms, which may aid in the development of a therapeutic strategy." (PMID 24141861, 2013). "APP, in turn, is cleaved by an asthma susceptible gene called ADAM33." (PMID 20513247, 2010). "Taken all considerations into account, the strongest evidence for true association between a previous candidate SNP and asthma in this population exists for rs528557 in ADAM33, while the signal from chromosome 17q21 is the most replicated finding from GWAS studies so far." (PMID 21103062, 2010). "The ADAM33 polymorphisms have also been related with asthma risk of smoking population." (PMID 20513247, 2010). "ADAM-33 therefore might play a key role in asthma-associated airway remodeling since the purified catalytic domain of this proteinase provokes an increased development of the vascular network in asthmatic patients." (PMID 20034386, 2009). "Howard and coworkers showed an association of ADAM33 with asthma in ethnically diverse populations." (PMID 19284602, 2009).
asthma (continued). "The effects on psoriasis of the two ADAM33 SNPs found associated with the disease in the univariate analysis were then tested by multivariate analysis adjusting for the effects of age, sex, asthma and rs3131000, one of the most strongly psoriasis-associated PSORS1 SNP in our data." (PMID 18560587, 2008). "ADAM33 is the first reported asthma-susceptible gene identified by positional cloning." (PMID 18778489, 2008). "Resolution of LD maps and block definition at ADAM33 locus is still noisy and it is likely that yet unidentified variant(s) within the ADAM33 gene or within distant regulatory elements may be responsible for asthma or psoriasis." (PMID 17878941, 2007). "ADAM33 has been identified as an asthma-associated gene in an out-bred population." (PMID 17640346, 2007). "In ADAM33 there are several SNPs that are associated with the asthma phenotype." (PMID 17640346, 2007). "Here, using a family-based association design to interrogate the locus, we identified several combinations of SNPs within ADAM33, a gene that has been associated with asthma in many studies, to be strongly associated with psoriasis in multigenerational French families." (PMID 17878941, 2007). "Although asthma is the complex disease with the largest number of genome scans (currently more than 15 studies), few genes have been associated with the disease (as far as we know; those are ADAM33, DPP10, PHF11, GPRA, and Vitamin D receptor)." (PMID 16115313, 2005). "In the same cohort (and replicated in an independent birth cohort) a negative association of the CG/GG-genotype of rs528557 in the ADAM33 gene with childhood asthma was found, confirming that genetic variation in the ADAM33 gene may be implicated in the progression of wheeze into childhood asthma." (PMID 37013496, 2023). "In addition, polymorphisms in ADAM33 are associated with adult-onset asthma and disease severity, and this gene and ADAM8 may contribute to the remodelling process that occurs with asthma progression." (PMID 26986948, 2016). "However, further investigations are clearly needed to discover functional ADAM33 gene polymorphisms and the role of genetic/epigenetic factors in conferring genetic susceptibility to environmental exposure induced asthma as well as biological function in asthma." (PMID 24817794, 2014). "Notably, the two ADAM33 genotypes, rs44707 and rs2787094, were also associated with asthma, which indicates the ADAM33 polymorphism may be the genetic basis of the association between asthma and the distinct palm pattern." (PMID 24141861, 2013). "As rs44707 and rs2787094 are associated with asthma and a distinctive palm pattern, the data suggest that ADAM33 polymorphisms are correlated with asthma and may be the underlying genetic basis of the association between asthma and palm dermatoglyphic patterns." (PMID 24141861, 2013). "Genetic variation in the MMP ADAM33 genes and the CD14 monocyte receptor has also been associated with allergic bronchitis and asthma, respectively." (PMID 40554352, 2025). "In these databases, curated relationships with ADAM33 included Asthma (UniProt, CTD and OMIM) and breast cancer (CTD)." (PMID 40110561, 2025). "Only then will it be possible to apply this knowledge to establish a new asthma therapy targeted towards ADAM33." (PMID 38396994, 2024). "Having taken under consideration ADAM33’s role in asthma development and pathogenesis, its use as a therapeutic target has been suggested." (PMID 38396994, 2024). "Although ADAM33′s role in asthma is evident, there is still a need for an in-depth analysis of the significance of particular SNPs among various populations as well as of the exact mechanism in which they exert their impact." (PMID 38396994, 2024). "This review summarizes the current knowledge on the genetic and functional aspects of ADAM33 in asthma pathogenesis." (PMID 38396994, 2024).